GOLGA2 (golgin A2)
Description:
Peripheral membrane component of the cis-Golgi stack that acts as a membrane skeleton that maintains the structure of the Golgi apparatus, and as a vesicle thether that facilitates vesicle fusion to the Golgi membrane (Probable). Required for normal protein transport from the endoplasmic reticulum to the Golgi apparatus and the cell membrane (By similarity). Together with p115/USO1 and STX5, involved in vesicle tethering and fusion at the cis-Golgi membrane to maintain the stacked and inter-connected structure of the Golgi apparatus. Plays a central role in mitotic Golgi disassembly: phosphorylation at Ser-37 by CDK1 at the onset of mitosis inhibits the interaction with p115/USO1, preventing tethering of COPI vesicles and thereby inhibiting transport through the Golgi apparatus during mitosis (By similarity). Also plays a key role in spindle pole assembly and centrosome organization. Promotes the mitotic spindle pole assembly by activating the spindle assembly factor TPX2 to nucleate microtubules around the Golgi and capture them to couple mitotic membranes to the spindle: upon phosphorylation at the onset of mitosis, GOLGA2 interacts with importin-alpha via the nuclear localization signal region, leading to recruit importin-alpha to the Golgi membranes and liberate the spindle assembly factor TPX2 from importin-alpha. TPX2 then activates AURKA kinase and stimulates local microtubule nucleation. Upon filament assembly, nascent microtubules are further captured by GOLGA2, thus linking Golgi membranes to the spindle. Regulates the meiotic spindle pole assembly, probably via the same mechanism (By similarity). Also regulates the centrosome organization. Also required for the Golgi ribbon formation and glycosylation of membrane and secretory proteins.
Synonyms: GM130; golgin-95; DEDHMB
Tractability: Antibody: UniProt places it where antibodies can reach, with high confidence. PROTAC: ubiquitination databases record sites on it; its protein half-life has been measured.
Gene: Protein-coding gene on chromosome 9 (128,255,829 to 128,276,026, reverse strand). Ensembl gene ENSG00000167110.
Subcellular location: Golgi apparatus, cis-Golgi network membrane; Endoplasmic reticulum-Golgi intermediate compartment membrane; Cytoplasm, cytoskeleton, spindle pole
Subcellular location (Human Protein Atlas): Golgi apparatus
Pathways (Reactome):
Vesicle-mediated transport: COPI-mediated anterograde transport; COPII-mediated vesicle transport
Cell Cycle: Golgi Cisternae Pericentriolar Stack Reorganization
Disease: Deregulated CDK5 triggers multiple neurodegenerative pathways in Alzheimer's disease models
Gene Ontology:
Molecular function: cadherin binding; identical protein binding; microtubule binding; protein binding; protein kinase binding; syntaxin binding; importin-alpha family protein binding
Biological process: centrosome cycle; endoplasmic reticulum to Golgi vesicle-mediated transport; glycoprotein biosynthetic process; Golgi ribbon formation; microtubule nucleation; mitotic spindle assembly; negative regulation of autophagy; negative regulation of protein binding; regulation of post-translational protein modification; spindle assembly; asymmetric cell division; Golgi disassembly; Golgi organization; meiotic spindle assembly; protein homotetramerization
Cellular component: cis-Golgi network; COPII-coated ER to Golgi transport vesicle; endoplasmic reticulum-Golgi intermediate compartment membrane; Golgi apparatus; Golgi cis cisterna; mitotic spindle; Golgi cisterna membrane; Golgi membrane; spindle pole
Genetic constraint (gnomAD): Loss-of-function variants: 31 observed, 102.77 expected, observed/expected ratio (o/e) 0.3, 90% interval 0.23 to 0.41. The upper end of that interval is the gene's LOEUF score, 0.41, which puts it in group 1 of 6, group 1 being the genes least tolerant of losing a copy. Missense variants: 969 observed, 1,062.6 expected, observed/expected ratio (o/e) 0.91, 90% interval 0.86 to 0.96. Synonymous variants: 419 observed, 425.68 expected, observed/expected ratio (o/e) 0.98, 90% interval 0.91 to 1.07.
Homologues: Orthologues: chimpanzee GOLGA2 (99% identical), macaque GOLGA2 (96% identical), chimpanzee GOLGA2 (96% identical), mouse Golga2 (75% identical), dog GOLGA2 (75% identical), tropical clawed frog golga2 (54% identical), zebrafish golga2 (47% identical), Drosophila melanogaster GM130 (23% identical), Caenorhabditis elegans golg-2 (20% identical). Paralogues in human: GOLGA6C (37% identical), GOLGA6A (37% identical), GOLGA6B (37% identical), GOLGA6D (37% identical), GOLGA8G (34% identical), GOLGA8S (34% identical), GOLGA8F (33% identical), GOLGA8M (31% identical), GOLGA8K (31% identical), GOLGA8N (31% identical), GOLGA8T (31% identical), GOLGA8Q (31% identical), and 6 more.
Diseases named in the same sentence as GOLGA2 in open-access papers:
GOLGA2 is named in the same sentence as 63 diseases in open-access papers, as found by Europe PMC text mining. Sharing a sentence is not in itself a finding about the gene and the disease. The quoted sentences say what the papers report.
lung carcinoma (7 papers, 2015 to 2022). "In two earlier studies, GOLGA2 downregulation inhibited tumorigenesis and cell invasion in gastric and lung cancers, suggesting that GOLGA2 appears to be an oncogene." (PMID 36552760, 2022). "FMNL1 was reported to regulate GOLGA2 distribution and expression during spindle formation in mouse oocytes, whereas GOLGA2 downregulation suppressed gastric and lung cancers invasion." (PMID 31861134, 2019). "In vivo mice model experiments show that down‐regulation of GOLGA2 suppresses lung cancer tumorigenesis by inhibiting angiogenesis and cell invasion." (PMID 28904855, 2017).
male infertility (6 papers, 2017 to 2024). The inability of the male to effect fertilization of an ovum after a specified period of unprotected intercourse. "It has previously been reported that the absence of GOLGA2 in gene-edited mice results in male infertility." (PMID 33831001, 2021).
viral infection (4 papers, 2023 to 2025). "Other genes that were down-regulated with viral infection (GOLGA2, IFI16, WDR81, HK2, SQSTM1, ULK1) remained down-regulated with NIC treatment (with and without virus)." (PMID 37901834, 2023).
gastric cancer (3 papers, 2018 to 2023). A primary or metastatic malignant neoplasm involving the stomach. "Gastric cancer involves numerous Golgi proteins such as GM130 (GOLGA2), GOLPH3, golgin-160 (GOLGA4), golgin-97 (GOLGA1) and golgin-84 (GOLGA7) that all play unique roles in cell processes including protein glycosylation, vesicle trafficking and Golgi structure maintenance." (PMID 37508488, 2023).
microcephaly (3 papers, 2021 to 2024). A congenital or acquired developmental disorder in which the circumference of the head is smaller than normal for the person's age and sex. "Recessive loss of function variants in GOLGA2 was linked to a neurological phenotype defined by microcephaly, seizures, and myopathy, in turn indicating the impact of GM130 on proper integrity and function of both the nervous system and skeletal muscle." (PMID 38470509, 2024).
prostate carcinoma (3 papers, 2016 to 2025). A carcinoma that arises from epithelial cells of the prostate gland. "In addition, GOLGA2 associates with the susceptibility to galectin‐1‐induced cell apoptosis in advanced prostate cancer." (PMID 28904855, 2017).
glioma (2 papers, 2022). A benign or malignant brain and spinal cord tumor that arises from glial cells (astrocytes, oligodendrocytes, ependymal cells). "In addition, we explored the proteins expressed by REEP6, LARP4B, CWC27, GOLGA2, ATP6AP1 and ERO1B in glioma patients through the HPA database, and REEP6, LARP4B, GOLGA2 and ATP6AP1 showed higher staining intensity in glioma than in normal brain tissue." (PMID 36552760, 2022).
glioblastoma multiforme (1 paper, 2019). "Conversely, FMNL1 downregulation suppressed glioblastoma multiforme cell migration and invasion via DIAPH1 and GOLGA2, respectively." (PMID 31861134, 2019).
Infertility (1 paper, 2022). "At the same time, knockout of GOLGA2 in mice specifically causes male gametogenesis impairment and leads to infertility." (PMID 35912115, 2022).
lung fibrosis (1 paper, 2020). "Recently, researchers have revealed that the deletion of GOLGA2 induced autophagy and lung fibrosis by disrupting the Golgi function, increasing alveolar macrophages and reducing subcellular lipid storage in GOLGA2 KO mice." (PMID 32724454, 2020).
schizophrenia (1 paper, 2018). A major psychotic disorder characterized by abnormalities in the perception or expression of reality. "In addition to CSPG4P11, which showed a significant SMR association with schizophrenia in the present study, these included CD46, encoding the CD46 complement regulatory protein, GOLGA2P7, encoding GOLGA2 pseudogene 2, and SLCO4C1, encoding Solute Carrier Organic Anion Transporter Family Member 4C1." (PMID 30419947, 2018).
infection (32 papers, 2012 to 2025). The state of being infected such as from the introduction of a foreign agent such as serum, vaccine, antigenic substance or organism. "In our study, JNK inhibitor could disturb GM130 polar distribution, and SAPK/JNK siRNA infection could also decrease the expression of Golga2 and Golga5 mRNA." (PMID 33770099, 2021).
tumor (14 papers, 2015 to 2026). "GOLGA2 (Golgi autoantigen, golgin subfamily A member 2) was the top risk gene and was upregulated in tumor tissues." (PMID 42093974, 2026). "Taken together, GOLGA2 splicing contributes to PTEN loss-of-function-induced secretion and tumor growth." (PMID 29921876, 2018). "Furthermore, GOLGA2 was a top-ranked gene in the signature and showed tumor-promoting effects in vitro, so it may warrant further study as a potential target." (PMID 42093974, 2026).
cancer (13 papers, 2016 to 2024). A tumor composed of atypical neoplastic, often pleomorphic cells that invade other tissues. "Previously, we reported that nuclear PTEN regulates the efficiency of alternative splicing of cancer-related genes, including GOLGA2, whose splicing promotes Golgi extension and secretion." (PMID 32249768, 2020). "GOLGA2 or GM130 regulates cell migration by realigning the Golgi apparatus towards its leading edge, while simultaneously playing an essential role in cancer cells through the regulation of Golgi glycosylation and protein transport across membranes." (PMID 37508488, 2023).
nervous system disease (3 papers, 2018 to 2023). "Indeed, mutation in the GM130-encoding gene (GOLGA2) leads to a human neurological disorder." (PMID 30403723, 2018).
myopathies (2 papers, 2023 to 2024). "Human genetic studies have identified pathogenic variants in critical proteins in the vesicular trafficking pathway, resulting in myopathies in affected patients such as GOLGA2, BIDC2 and BET1." (PMID 37432316, 2023).
GOLGA2 also shares sentences with these, for which no sentence is quoted: breast carcinoma (8 papers); Ataxia (5); neurodegenerative disease (4); acute pancreatitis (3); Alzheimer disease (2); Arrhythmia (2); colorectal cancer (2); endometrial cancer (2); leukemia (2); multiple myeloma (2); Muscular dystrophies (2); amyotrophic lateral sclerosis (1); anaplastic thyroid carcinoma (1); cardiomyopathy (1); Cerebellar atrophy (1); Chlamydia infection (1); cholangiocarcinoma (1); colon cancer (1); colorectal adenocarcinoma (1); COVID-19 (1); cyst (1); cystinosis (1); developmental delay (1); diabetes (1); endotoxemia (1); Globozoospermia (1); HCMV infection (1); hepatitis B virus infection (1); hepatoma (1); laryngeal squamous cell carcinoma (1).
A further 17 diseases each share a sentence with GOLGA2 in 1 paper.